BRCA1 (BRCA1 DNA repair associated)
Diseases named in the same sentence as BRCA1 in open-access papers (continued):
Sharing a sentence is not in itself a finding about the gene and the disease.
tumor (continued). "Pathogenic BRCA1/2 mutations confer an increased risk of developing neoplasms, especially of the breasts and ovaries: in our series, three patients with these PVs showed a typical phenotype, highly consistent with the syndrome (including the patient with double mutation)." (PMID 36980738, 2023). "Our data suggests that the loss of the BRCA1 tumor-suppressor gene may potentially drive the activation of the TAZ oncogene." (PMID 37887275, 2023). "However, no significant connections were discovered between risk score and tumor stage, tumor grade, therapy type, or BRCA1 type (p > 0.05)." (PMID 36726489, 2023). "SLUG accumulation in basal-like tumours is also associated with BRCA1 mutations." (PMID 37627137, 2023). "All small sequencing BRCA1/2 pathogenic variants were detected in germline and tumour DNA." (PMID 38201604, 2023). "Both BRCA1-mutated and BRCA1-methylated neoplasms have similar pathological features." (PMID 37240365, 2023). "Instead, germline testing could be reserved for women who have a BRCA1/2 pathogenic variant detected first in tumour DNA, or when tumour testing fails." (PMID 36765687, 2023). "All BRCA1 methylated tumours showed LOH of the second BRCA1 allele." (PMID 37029129, 2023). "Consequently, tumor cells with deficient BRCA1/2 genes are unable to repair DNA damage through HRR and rely on PARP proteins for the restoration of single-strand breaks (SSBs)." (PMID 37629155, 2023). "This identified all tumours with germline BRCA1/2 loss (22 cases out of 560), 22 further cases of somatic BRCA1/2 loss and 47 tumours with BRCA1/2 deficiency where no mutation was detected, but it was limited by the requirement of whole-genome sequencing for data input." (PMID 36831687, 2023). "The identified substructure among the mutationally quiescent non-BRCA1/BRCA2 tumours may point to common aetiological mechanisms within the subgroups." (PMID 37316882, 2023). "In one case report, a patient demonstrated a radiographic complete response to this olaparib/pembrolizumab combination in the maintenance setting, albeit in the atypical context of harboring both a germline BRCA1 mutation and an extremely high tumor mutational burden." (PMID 37509318, 2023). "The higher expression of neoantigens as a result of greater tumour mutational burden in BRCA1-mutated tumours may in part account for the superior immune cell attraction and infiltration." (PMID 38017453, 2023). "In addition, in four patients informative for methylation allele specificity in WBC, we found the tumor samples to reveal low-level BRCA1 methylation, likely reflecting a fraction of benign cells in the biopsy." (PMID 38053165, 2023). "This approach is exemplified by poly adenosine diphosphate-ribose polymerase (PARP) inhibitors, which have received regulatory approval to treat patients with multiple tumor types with BRCA1 or BRCA2 (BRCA1/2) loss-of-function (LOF) mutations and other selected alterations in different settings." (PMID 37277454, 2023). "Therefore, patients with this type of tumor are at potentially high risk of ipsilateral or contralateral recurrence, and risk-reduction mastectomy is strongly considered in patients with BRCA1 mutation." (PMID 36737474, 2023). "Interrogating tumour DNA for gene-specific loss of heterozygosity in germline carriers of non-BRCA1/2 HRR pathogenic variants may help to clarify whether borderline GIS-negative tumours have biallelic inactivation and are more likely to respond to PARPi." (PMID 36765687, 2023). "In the evaluable intent-to-treat population (N = 60), 58 (97%) patients harbor ≥1 BRCA1/2 mutation(s) in tumor sequencing, with 95% (53/56) concordance between germline and tumor mutations, and 85% (40/47) of evaluable patients have BRCA locus loss of heterozygosity indicating HRD." (PMID 37803017, 2023).
tumor (continued). "Mutations in POLE and a frameshift deletion in BRCA1 were observed in the parental tumor tissue in each of the six cases, and additional genomic alterations, which were not apparently related to histopathological and immunohistochemical alterations, were found in the PDXs of these cases." (PMID 37231035, 2023). "Indeed, while the majority of cells constituting the tumor mass demonstrate the loss of the wild-type BRCA1 allele, there is a small fraction of BRCA1-proficient malignant cells which are resistant to therapeutic pressure and undergo expansion during NACT." (PMID 36768191, 2023). "Indeed, in all patients tested, the addition of four HRR genes brought about a very small uplift in the potential causes of HRD in BRCA1/2 wild type/GIS-positive tumours, with only 2/35 additional pathogenic variants identified." (PMID 36765687, 2023). "Moreover, for BRCA1 mutation carriers, nFTH1 expression in the tumor was associated with smaller tumor size (p = 0.045) and positive HER2 status (p = 0.049), while in BRCA2 mutation carriers, nFTH1 expression was associated with positive ER status (p = 0.004)." (PMID 38201455, 2023). "We performed all analyses separately for the ER-negative and ER-positive patient groups, corresponding to the specific PREDICT models for ER-negative and ER-positive breast cancer and the characteristic tumor phenotypes of the BRCA1 and BRCA2 variant carriers, respectively." (PMID 37173335, 2023). "Of the 36 germline BRCA1/2 pathogenic variants, 33 were detected in tumour DNA." (PMID 38201604, 2023). "In addition, Cavin-3 can interact with breast cancer susceptibility gene 1 (BRCA1), and its loss of expression can affect BRCA1-mediated tumor inhibition." (PMID 37828916, 2023). "Intraindividually, BRCA1 epimutations affected the same allele in normal and tumor cells." (PMID 38053165, 2023). "We first conducted univariate analysis to define whether tumor stage, tumor grade, debulking status, age, or BRCA1/2 mutation status were independently associated with survival outcomes among treatment-naïve patients." (PMID 38318505, 2023). "A subset of tumor tissues from 59 patients, were sequenced with a tissue panel, and no additional somatic BRCA1/2 mutations were identified, supporting the primary somatic BRCA1/2 analysis with Guardant360 on ctDNA." (PMID 37773077, 2023). "For single-cell RNA sequencing data, modeling this association had a shrinkage effect on the variability estimates (and means to a lesser extent), something obvious for the BRCA1 dataset for cell types with low abundance (e.g., tumor-associated macrophages, Tam1)." (PMID 37549298, 2023). "All germline BRCA1/2 pathogenic small sequencing variants were detected in tumour DNA." (PMID 38201604, 2023). "However, despite decades of extensive research, the mechanisms underlying BRCA1’s contribution to tissue-specific tumor development remain elusive." (PMID 37762577, 2023). "Recently, the evidence that about 1/3 of BRCA1/2 pathogenic variants in OC patients are confined to the tumor tissue, has led to a recommendation that BRCA analysis be performed on DNA extracted from cancer tissue, in order to detect both the constitutional and the somatic variants." (PMID 36900320, 2023). "Tumours with BRCA1 or BRCA2 mutations are highly sensitive to PARP inhibitors." (PMID 36010882, 2022). "Platinum-based chemotherapy may have anti-tumor activity in mCRPC patients with HRR mutations (e.g. BRCA1/2m)." (PMID 35924163, 2022). "Interestingly, we found that the presence of BRCA1 somatic mutation indicated a worse tumor response (P = 0.038)." (PMID 35337339, 2022). "Whether its inhibitory effects extend to BRCA1/2‐deficient cells and tumours remains to be evaluated." (PMID 35107878, 2022). "The underlying mechanism might be that cediranib could increase tumor hypoxia and inhibit platelet-derived growth factor receptor to downregulate BRCA1/2 and RAD51, thus decreasing a homology-deficient DNA repair to confer olaparib sensitivity." (PMID 35466318, 2022).
tumor (continued). "According to the Knudson hypothesis, also known as the two-hit hypothesis, in the case of most tumor-suppressor genes (such as BRCA1 and BRCA2), both alleles need to be inactivated to cause a phenotypic change." (PMID 35626055, 2022). "Therefore, it should include genetic counselling and the ascertainment of germline or somatic nature of every BRCA1/2 alteration identified in the tumor to direct the risk assessment and the following preventive actions for the woman itself and her relatives." (PMID 35406410, 2022). "Moreover, our genetic analysis of OC tumor DNA from this carrier revealed the loss of the wild-type allele and retention of the BRCA1 variant allele." (PMID 35456503, 2022). "Restoration of the functional HRR pathway in a HRD tumor may occur via BRCA1/2 or HR gene reversion mutation which functionally restores protein activity." (PMID 36577523, 2022). "Recently, Pol θ emerged as a new promising drug target to trigger the synthetic lethality between loss of the PolQ gene and deficiencies in DSB DNA repair-related tumor suppressor genes including BRCA1/2, ATM and FANCD2 for the treatment of HDR-deficient tumors." (PMID 35463312, 2022). "Somatic mutations of the tumor-suppressor genes BRCA1 and BRCA2 have also been reported in CCA." (PMID 34312770, 2022). "While germline and somatic BRCA1/2 variants are currently considered the most clinically relevant, patients with variants in other HR pathway genes (either in germline or tumour) may also benefit from PARPi therapy." (PMID 36011309, 2022). "Specifically, tumour testing for BRCA1/2 variants can identify more patients who might be eligible for PARPi treatment." (PMID 36011309, 2022). "However, since the implementation of reflex tumour testing for BRCA1/2 variants, one institution has seen improvements in the rate of genetic referral (12.88% versus 7.10%) and time to genetic counselling appointment (59 days versus 33 days)." (PMID 36011309, 2022). "BRCA1/2-mutation status was confirmed by sequencing of DNA extracted from tumours in all cases." (PMID 35501389, 2022). "The higher PBC mortality before menopause could be explained by a more aggressive tumor biology and higher hereditary risk due to BRCA1 mutations." (PMID 35577853, 2022). "We sought to explore the incidence of BRCA1/2 reversion mutations in different tumor types." (PMID 36557020, 2022). "Thus, in addition to inflicting replication‐associated DNA damage and suppressing PARP1/2‐dependent DNA repair, PARPis act by enhancing the immunogenicity of BRCA1/2‐deficient tumours, thereby facilitating their elimination by the immune system." (PMID 35107878, 2022). "Among the 86 tumor samples analyzed, 7 harbored BRCA1/2 mutations." (PMID 35246547, 2022). "However, it will be important in future work to assess the influence of tumor genotype in the response to HKMTI-1–005 in light of recent data showing that BRCA1 deficiency drives inflammation that supports both immunoreactivity and immune resistance." (PMID 35131874, 2022). "A key mechanism of action of pyridostatin is activation of cGAS/STING‐dependent innate immune responses, which may underlie its efficacy against BRCA1/2‐mutated tumours in vivo." (PMID 35107878, 2022). "OlympiAD Trial is a phase III study which enrolled MBC patients with both triple-negative and HR+/HER2- tumours carrying a BRCA1/2 germline mutation, who had received a maximum of two lines of chemotherapy, to receive the PARPi olaparib or physician’s choice single-agent chemotherapy." (PMID 35954393, 2022). "Moreover, the correlation between tumor size and lymph node involvement in BRCA1 mutation carriers has been reported to be weaker than for sporadic BC or BRCA2-associated BC." (PMID 35507134, 2022). "A more recent suggestion is that tissue-dependent tumor-suppression of BRCA1 may be associated with its roles in transcriptional and epigenetic regulation." (PMID 35327946, 2022).
tumor (continued). "In a xenograft mouse model, the polarization of the tumor-associated (M2) macrophage and the expression of breast cancer gene 1 (BRCA1), human epidermal growth factor receptor 2 (HER2), vascular endothelial growth factor (VEGF), and tumor necrosis factor (TNF)-α were measured." (PMID 36118080, 2022). "In vivo anti‐tumour efficacy of pyridostatin on BRCA1‐deficient human PDTXs." (PMID 35107878, 2022). "Importantly, triple negative BCa is often associated with mutations in DNA repair genes such as BRCA1, making the therapeutic targeting of the pathway a viable option for the difficult to treat tumor type." (PMID 36315513, 2022). "We tested the hypothesis that the inactivation of the WT allele at the tumor level could argue in favor of BRCA1 variant pathogenicity." (PMID 35039532, 2022). "BRCA1‐deleted tumours can acquire PARPi resistance via loss of 53BP1, REV7 or the shieldin complex." (PMID 35107878, 2022). "The increased cytotoxicity in TNBC cell lines may be because of shared characteristics with BRCA‐1 deficient tumours, commonly known as sporadic BRCAness." (PMID 35841287, 2022). "We initially assessed LOH status in matched primary and recurrent tumors to determine whether BRCA1/2 deficiency varied over the course of tumor evolution." (PMID 36344544, 2022). "According to the American College of Medical Genetics and Genomics (ACMG) guidelines, any patient with a known pathogenic or likely pathogenic variant in BRCA1/2 in any tumor type should be further investigated with germline testing to look for germline mutations." (PMID 36577523, 2022). "In another example of epigenetic adaptation following chemotherapy, while sensitivity to PARP inhibitors of HGSOC is associated with DNA methylation at BRCA1, tumours recurring following chemotherapy restore BRCA1 expression associated with reduced DNA methylation." (PMID 35326684, 2022). "Nevertheless, targeted germline and/or tumor BRCA1/2 mutation testing may be a potential alternative approach." (PMID 35813356, 2022). "Reflex tumour testing of BRCA1/2 mutations at the time of diagnosis of advanced EOC can allow for a turnaround of 3–4 weeks and can detect the majority of germline mutations and is thus encouraged to optimize testing efficiency and increase the rate of BRCA1/2 mutation detection." (PMID 35735457, 2022). "Co-staining for CK18 and S100a9 in the mammary epithelium at multiple developmental stages, tumor-adjacent and tumor tissues also revealed increased S100a9 protein levels, indicating that loss of Brca1 stimulates S100a9 expression at both the mRNA and protein levels in mammary tissues." (PMID 35304461, 2022). "As previously reported, BRCA1 reversion mutations have been associated with the functional reactivation of HR and have been reported both in cell lines and in PARPi pre-treated human tumor samples." (PMID 35406579, 2022). "To check whether high BRCA1 expression was significantly associated with tumor proliferation, we calculated the proportions of luminal B tumors in the low- and high-BRCA1 expression groups." (PMID 34996912, 2022). "TNBCs may be susceptible to DNA repair inhibitors because these tumours have lower expression of BRCA‐1/2 or of genes involved in DNA repair pathways." (PMID 35841287, 2022). "Consequently, BRCA1/2 inactivation is associated with accumulation of stalled forks, replication‐associated DNA damage and genome instability that can drive tumour formation." (PMID 35107878, 2022). "For example, deletions of BRCA1/2 leads to DNA damage repair deficiencies in certain tumours, and tumours with a large fraction of complex SVs generate vast amounts of neoantigens that may confer susceptibility to immune therapies." (PMID 35355264, 2022).
tumor (continued). "The synergy of a combined EZH2/ATM inhibition in BRCA1-deficient tumor cells could be demonstrated by using several small molecule inhibitors of EZH2 (GSK126, ZLD1039) and ATM (AZD1390, KU60019) that are currently at various stages of preclinical development." (PMID 35715861, 2022). "BRCA-1 mutated tumor cells mainly rely on PARP-mediated DNA repair." (PMID 36278891, 2022). "Also, OC tumours are known to genetically change over time, in terms of tBRCAmut status and possible BRCA1/2 reversion mutations, but their larger genomic scar patterns detected by genomic instability testing remain quite stable over time." (PMID 35781107, 2022). "In addition, PPP1CA can bind to cyclin D1 to phosphorylate RB or can dephosphorylate breast cancer susceptibility protein-1 (BRCA1), all of which induce cell cycle deregulation and promote tumor cell proliferation." (PMID 34964699, 2022). "Notably, MLPA analysis on the DNA from the non-neoplastic tissue from PA3 case was able to highlight the pathogenic deletion of exon 16 of BRCA1, previously identified in the tumor sample." (PMID 35625944, 2022). "A similar principle could also be extended to the inhibition of SIRT6 in BRCA1/2 deficient tumor, resulting in post-replication DSBs." (PMID 35203541, 2022). "Germline assessment alone will miss approximately 7% of patients who harbour somatic BRCA1/2 mutations and tumour testing alone may miss approximately 5% of patients who have germline mutations due to decreased test sensitivity and coverage." (PMID 35735457, 2022). "Importantly, the loss of BRCA1 expression was found to be significantly associated with DGC, a higher tumor grade, advanced clinical stage, and a lower 2-year survival rate compared to patients with positive BRCA1 expression." (PMID 36497436, 2022). "Based on clinical germline or tumor testing performed prior to enrollment, 19 patients had a germline BRCA1 (n = 6) or BRCA2 (n = 13) mutation, and 1 had a germline PALB2 mutation; 2 patients had a BRCA2 variant of uncertain significance (VUS) and 1 patient had a PALB2 VUS." (PMID 35750695, 2022). "Next, we tested whether expression of BRCA2-001/Short affected overall survival across 67 BRCA1/2 mutation carriers (from discovery and validation cohorts) for whom we had survival data and RNA sequenced from at least one tumor." (PMID 36344544, 2022). "Moreover, BRCA1-reconstituted tumor cells are more sensitive to histone deacetylase (HDAC)-inhibitor-induced loss of stem cell function corresponding to a BRCA1-deficient phenotype." (PMID 36612206, 2022). "Moreover, we demonstrate that pyridostatin shows anti‐tumour efficacy in BRCA1‐deficient, PARPi‐resistant tumour models, including patient‐derived xenografts." (PMID 35107878, 2022). "The cells with compromised BRCA1 or BRCA2 (BRCA1/2) function accumulate stalled replication forks, which leads to replication‐associated DNA damage and genomic instability, a signature of BRCA1/2‐mutated tumours." (PMID 35107878, 2022). "However, only one clinical trial has so far investigated the cisplatin sensitivity in PARPi‐resistant BRCA1‐deficient tumours." (PMID 35107878, 2022). "Mutations in BRCA1 induce the generation of hydrogen peroxide in tumor cells and in the stroma." (PMID 35053485, 2022). "Recent studies have revealed that anti-PD-1/PD-L1 blockade improves patient survival in PD-L1-positive patients, and PARP inhibitors have also shown significant tumor response in patients with germline breast cancer associated gene 1/2 (BRCA1/2)-positive advanced TNBC." (PMID 35626017, 2022). "Most individuals in this study reported tumour genetic testing may help their doctors direct their treatment, but many thought that BRCA1/2 PV variants seen in tumour tissue were always inherited from a parent." (PMID 35418215, 2022). "Ninety-seven tumor samples were analyzed from 26 different BRCA1 variants." (PMID 35039532, 2022).